CTSL (cathepsin L)
Diseases named in the same sentence as CTSL in open-access papers (continued):
Sharing a sentence is not in itself a finding about the gene and the disease.
invasive carcinoma (3 papers, 2015 to 2024). A carcinoma that is not confined to the epithelium, and has spread to the surrounding stroma. "In the constitutive model of PNET progression—RT2—the proliferation rate in advanced stages of tumor progression (insulinomas and invasive carcinomas) in the cathepsin L-deficient background was significantly reduced by ~90% when compared to control tumors with WT CTS L." (PMID 25927437, 2015). "We found that cathepsin L1, serpin B12 and mucin-19 were highly expressed in mice at the initial stage of disease, whereas Ig Alpha Chain C Region (IGHA) and Complement C3 were enriched in animals with invasive carcinoma." (PMID 35798767, 2022).
ischemia (3 papers, 2017 to 2024). A hypoperfusion of the BLOOD through an organ or tissue caused by a PATHOLOGIC CONSTRICTION or obstruction of its BLOOD VESSELS, or an absence of BLOOD CIRCULATION. "Immunoreactive cathepsin L was found in the ischemic core of both primate and murine models about 2 h after onset of ischemia." (PMID 41541591, 2022). "Ex vivo protease secretion assays and extracellular matrix degradation assays showed that cathepsin L release during ischemia disturbed micro-vessel integrity." (PMID 41541591, 2022). "Activated macrophages secrete TNFα and cathepsin L, which stimulate further production and activation of heparanase by these cells and by ischemia-induced renal injured cells." (PMID 28388547, 2017).
ischemic stroke (3 papers, 2020 to 2023). A stroke disorder caused by obstruction of blood flow to the brain, due to thrombotic (local blood clot formation) or embolic (due to a blood clot or other material traveling from another site) event. "In research on ischemic stroke, it was indicated that inhibition of cathepsin L expression in astrocytes contributes to neuronal protection." (PMID 37065920, 2023). "Using immunohistochemical staining, mass spectrometry, and other assays, the increase of cathepsin L in the brain was correlated with extracellular matrix and perlecan degradation after ischemic stroke." (PMID 41541591, 2022). "More research is needed to elucidate cathepsin L's role in post-stroke inflammation and brain damage, in order to further explore the factors contributing to worsened patient outcome after ischemic stroke and work toward finding better therapeutic interventions." (PMID 41541591, 2022). "MMP-2, MMP-3 and cathepsin L showed a smaller AUC and had no predictive effects on ischemic stroke." (PMID 32982940, 2020).
kidney damage (3 papers, 2021 to 2025). "Since E64 can inhibit caspases, protection of the extracellular matrix from CTSL activity represents an additional mechanism for E64-mediated protection from enterococcal dissemination and kidney damage and suggests that the interaction between CTSL and caspases deserves further investigation." (PMID 40980878, 2025). "Our previous studies have also found that over-expressed CTSL could aggravate kidney damage via activating intracellular complement system and inducing endothelin-1 signaling to promote the release of inflammatory cytokines." (PMID 34393767, 2021). "Emerging evidence implicates Cathepsin L (CTSL) in diabetic complications, including nephropathy and retinopathy." (PMID 39150053, 2024).
kidney failure (3 papers, 2022 to 2025). An acute or chronic condition that is characterized by the inability of the kidneys to adequately filter the blood. "We tested the dual assay with human Cathepsin-L,dysfunction of which is a hallmark of several diseases, includingCOVID-19, kidney failure, and cancer." (PMID 40705439, 2025).
metastatic carcinoma (3 papers, 2013 to 2021). A carcinoma which has spread from the original site of growth to another anatomic site. "Thus, our findings suggest a potential role of platyphyllenone in modulating cathepsin L-induced epithelial–mesenchymal transition in human oral cancer, which may have vital therapeutic implications in managing metastatic carcinomas." (PMID 34065077, 2021).
oral cancer (3 papers, 2016 to 2023). "Protein and mRNA overexpression of cathepsin L is frequently detected in oral dysplastic lesions, and their higher levels may be closely associated with the development of oral cancer." (PMID 37334378, 2023). "Taken together, our study indicates that platyphyllenone exerts significant anti-metastatic effects on oral cancer cells by modulating cathepsin L expression, the MAPK signaling pathway, and the epithelial–mesenchymal transition process." (PMID 34065077, 2021). "The role of cathepsin L in oral cancer progression has not been completely known, though." (PMID 37334378, 2023). "Specifically, we assessed the expressions of cathepsin L (CTSL), cathepsin S (CTSS), cathepsin A (CTSA), and cathepsin Z (CTSZ) in platyphyllenone-treated oral cancer cells." (PMID 34065077, 2021).
osteosarcoma (3 papers, 2007 to 2023). A usually aggressive malignant bone-forming mesenchymal neoplasm, predominantly affecting adolescents and young adults. "One study used antisense oligonucleotides to cathepsin L and demonstrated decreased migration and in vitro invasion of human osteosarcoma cells." (PMID 17488522, 2007).
pancreatic adenocarcinoma (3 papers, 2020 to 2022). "Results showed the upregulation of CTSL/B and ACE2 in Pancreatic adenocarcinoma (PAAD) and Stomach adenocarcinoma (STAD) and demonstrated a positive correlation between copy number alteration (CNA) and gene expression for CTSB in PAAD and STAD." (PMID 33231569, 2020).
parasite infection (3 papers, 2013 to 2024). "Cathepsin L has been considered an important target for the prevention of parasitic infections and has been extensively studied in Schistosoma hepatica, Schistosoma mansoni, and Taenia solium, but limited studies have been conducted on T. spiralis cathepsin L." (PMID 35739604, 2022). "The fluke burden of goats vaccinated with cathepsin L1 (group 2: DPWWLKQ) and cathepsin L1 (group 3: SGTFLFS) was significantly correlated with total IgG, reflecting the importance of antibodies in protecting against parasite infection." (PMID 39000332, 2024). "Here, we have produced a standardized test using a highly stable recombinant form of cathepsin L1, FhCL1, which exhibits high sensitivity and specificity and with no cross-reaction with other parasitic diseases." (PMID 24069474, 2013).
prostate tumor (3 papers, 2012 to 2020). "The relationships between prostate tumor Ki67 and CTSL and weight loss associated changes in FFAs, lean mass, and fecal microbiota warrant further investigation." (PMID 33042834, 2020). "The average concentration of CTSL measured was 6.30 ± 2.06 ng/mg total protein for normal tissues and 11.83 ± 4.56 ng/mg total protein for prostate tumors." (PMID 24289299, 2013). "Subsequently, using the in-house developed method, we estimated the epithelium percentage of the 8 normal prostate tissues and 36 prostate tumors whose EpCAM and CTSL levels were measured." (PMID 24289299, 2013). "Compared to normal tissues, immunoassay data showed that both EpCAM and CTSL expression were significantly increased in prostate tumors with a 4.75 fold increase for EpCAM and a 1.88 fold increase for CTSL." (PMID 24289299, 2013). "With EpCAM and CTSL expressions in prostate tumor tissues, we demonstrated that normalization by epithelial percentage is useful in analyzing ELISA results for epithelial proteins." (PMID 24289299, 2013). "While ELISA itself misleadingly showed a significant increase of CTSL in prostate tumors, with normalization by epithelium percentage, ELISA analysis also showed that CTSL expression was comparable between these two groups." (PMID 24289299, 2013). "This pathway activates several downstream genes, such as cathepsin L, that play a role in prostate tumor invasiveness." (PMID 23185449, 2012). "Medium to strong staining of CTSL was observed in all 6 prostate tumor cases." (PMID 24289299, 2013). "With IHC staining carried out in this study and in a previously published study, we showed that CTSL expression was not significantly different between normal tissue and prostate tumors after epithelium normalization." (PMID 24289299, 2013). "In contrast to the significant elevated CTSL expression in prostate tumors from ELISA results without normalization by epithelial content, CTSL expression was comparable between normal tissues and prostate tumors after epithelium normalization." (PMID 24289299, 2013).
Stroke (3 papers, 2018 to 2025). Sudden impairment of blood flow to a part of the brain due to occlusion or rupture of an artery to the brain. "Cathepsin L, a cysteine protease known for degrading tissues in lysosomes and elsewhere, may play a role in brain tissue loss and inflammation after stroke." (PMID 41541591, 2022). "Our preliminary data have demonstrated that cathepsin L is significantly increased in plasma from stroke patients compared to controls." (PMID 41541591, 2022). "Studies have suggested that cathepsin L appears in the ischemic core shortly after stroke is induced." (PMID 41541591, 2022). "We evaluated levels of cathepsin L in plasma of 30 acute stroke patients (stroke onset within 24 h, confirmed by MRI) compared to age matched controls by enzyme-linked immunosorbent assay." (PMID 41541591, 2022). "After stroke, Cathepsin L may indirectly affect autophagy through activation of the cathepsins–tBid–mitochondrial apoptotic signaling pathway." (PMID 41541591, 2022). "However, it is unclear if cathepsin L is a key culprit that exacerbates stroke evolution, and more research needs to be done to further evaluate the translational value by targeting cathepsin L in stroke." (PMID 41541591, 2022). "The data suggest that cathepsin L offers a translational significance in stroke." (PMID 41541591, 2022). "In preclinical stroke models, pharmacological inhibition of cathepsin L reduced infarct volume and improved neurobehavioral outcomes, though it remains unclear whether cathepsin L actively contributes to infarct expansion or simply reflects secondary inflammatory processes." (PMID 40869205, 2025). "In addition, research has shown that active cathepsin L released during stroke may play a role in degradation of micro-vessel tissues, worsening stroke outcome." (PMID 41541591, 2022).
abdominal aortic aneurysm (2 papers, 2017 to 2022). Enlargement and ballooning of the vessel that supplies arterial blood to the abdomen, pelvis and legs. "In addition, plasma cathepsin L was found to be higher in patients with abdominal aortic aneurysm." (PMID 29149174, 2017).
acute pancreatitis (2 papers, 2024 to 2025). An acute inflammatory process that leads to necrosis of the pancreatic parenchyma. "Our next aim was to elucidate the molecular mechanisms underlying our observation that under conditions of acute pancreatitis, CST3 lost its capacity to inhibit CTSB and CTSL-supporting disease progression." (PMID 39962054, 2025). "Both, cathepsin B (CTSB) and L (CTSL) are central regulators of protease activation in acute pancreatitis." (PMID 38709385, 2024). "In pancreas-specific CTSB and CTSL double knockout undergoing with caerulein-induced acute pancreatitis intrapancreatic trypsin activity was increased while disease severity was not affected when compared to wildtypes or mice with pancreas-specific single CTSB or CTSL knockout." (PMID 38709385, 2024).
Atrophy (2 papers, 2015 to 2023). Any weakening or degeneration, especially through lack of use. "Though FoxO-1 is related to lysosomal atrophy, the mRNA level of cathepsin-L only slightly increased in our experiment." (PMID 25797259, 2015). "In a rat atrophy model, AX was shown to inhibit proteolysis and oxidative stress by decreasing the expression of CuZn-SOD, HSP72, cathepsin L, calpain and ubiquitin in the atrophied muscle." (PMID 38201863, 2023).
brain cancer (2 papers, 2014 to 2021). A primary or metastatic malignant neoplasm affecting the brain. "Genes involved in lysosomes/phagosomes, endocytosis, or autophagy (e.g., tartrate-resistant acid phosphatase type 5-like, cathepsin L, deleted in malignant brain tumors 1) were among those increased in expression during uptake of symbionts." (PMID 33614268, 2021).
brain tumor (2 papers, 2014 to 2018). "The invasive ability of brain tumor cells was markedly reduced by full-length antisense cDNA of CTSL." (PMID 25384089, 2014). "Stat3 upregulates the expression of lysosomal proteases cathepsin‐B and cathepsin‐L under physiological conditions and, thus, may facilitate cathepsin‐B enhanced tissue invasion and lysosomal‐mediated cell death regulation in brain tumors." (PMID 29949238, 2018).
celiac disease (2 papers, 2022 to 2023). An autoimmune genetic disorder with an unknown pattern of inheritance that primarily affects the digestive tract. "Therefore, we evaluated the activity of T. castaneum cathepsin L as a prospective candidate for the development of an effective pharmaceutical for the therapy of celiac disease and other gluten intolerances." (PMID 35806001, 2022).
coronary artery stenosis (2 papers, 2017 to 2022). "One hospital-based study found a rather strong correlation of serum cathepsin L levels and the degree of stenosis in the left anterior descending coronary artery patients with coronary artery stenosis and that subjects with stenosis had higher cathepsin L levels than subjects without." (PMID 29149174, 2017).
Esophageal carcinoma (2 papers, 2022). A primary or metastatic malignant neoplasm involving the esophagus. "Further, CTSL, FURIN, NRP1 and SCARB1 gene expression levels were significantly higher in esophageal carcinoma (ESCA) samples in comparison to their normal matches." (PMID 35970857, 2022).
focal segmental glomerulosclerosis (2 papers, 2019 to 2025). A renal disorder characterized by sclerotic lesions in the glomeruli. "Interestingly, CTSL expression is increased in many glomerular diseases, such as membranous glomerulonephritis, minimal change disease, and focal segmental glomerulosclerosis." (PMID 40980878, 2025).
folate deficiency (2 papers, 2019 to 2024). A nutritional condition produced by a deficiency of FOLIC ACID in the diet. "Supplementing with 5-formyltetrahydrofolate successfully prevented the swim bladder anomaly and the imbalanced expression of cathepsin L and the zCSTB-like protein induced by folate deficiency." (PMID 31477754, 2019). "Folate supplementation effectively mitigated the impaired autophagy and lipid accumulation caused by the inhibition of cathepsin L activity, even when the inhibition was not directly related to folate deficiency." (PMID 38956599, 2024).
glomerular diseases (2 papers, 2016 to 2025). "The importance of podocyte cathepsin L is highlighted by both in vitro data and animal models of glomerular diseases, as well as expression studies of human biopsies." (PMID 27855638, 2016).
gram-positive bacterial infections (2 papers, 2021 to 2022). Infections caused by bacteria that retain the crystal violet stain (positive) when treated by the gram-staining method. "Teicoplanin, a glycopeptide antibiotic used to treat Gram-positive bacterial infections prevents the early step of the viral life cycle by inhibiting cathepsin L in the late endosome/lysosome and blocking the entry of pseudo-typed viruses for Ebola, MERS-CoV and SARS-CoV-1." (PMID 34755538, 2021).
Hyperinsulinemia (2 papers, 2021 to 2024). An increased concentration of insulin in the blood. "Metformin and hyperinsulinemia changed the expression of extracellular proteins (e.g. metformin: CTSL, EGFR, IL5, KLK3; insulin: IL4, IL15, PGC, SORL1)." (PMID 33690729, 2021). "It is unclear whether the increased CTSL activity/concentration is solely a result of hyperglycemia or the corresponding hyperinsulinemia, and further clarification is needed." (PMID 39150053, 2024). "Hyperinsulinemia, however, did not change GUSB, slightly decreased CTSL expression and increased TFRC levels, all of these changes being significantly different from the metformin effects." (PMID 33690729, 2021).
invasive breast carcinoma (2 papers, 2019 to 2025). A carcinoma that infiltrates the breast parenchyma. "Moreover, CTSL is abundantly expressed in both tumour and stromal compartments of invasive breast cancer tissues." (PMID 41261048, 2025).